ENSG00000256646 (novel PSMA2 and C7orf25 readthrough)
Gene: Protein-coding gene on chromosome 7 (42,909,273 to 42,932,214, reverse strand). Ensembl gene ENSG00000256646.
Genetic constraint (gnomAD): Loss-of-function variants: 2 observed, 15.68 expected, observed/expected ratio (o/e) 0.13, 90% interval 0.051 to 0.4. Missense variants: 67 observed, 130.92 expected, observed/expected ratio (o/e) 0.51, 90% interval 0.42 to 0.63. Synonymous variants: 48 observed, 47.43 expected, observed/expected ratio (o/e) 1.01, 90% interval 0.8 to 1.29.